TRMO (tRNA methyltransferase O)
Description:
S-adenosyl-L-methionine-dependent methyltransferase responsible for the addition of the methyl group in the formation of N6-methyl-N6-threonylcarbamoyladenosine at position 37 (m(6)t(6)A37) of the tRNA anticodon loop of tRNA(Ser)(GCU). The methyl group of m(6)t(6)A37 may improve the efficiency of the tRNA decoding ability (By similarity).
Synonyms: C9orf156; HSPC219; NAP1
Tractability: PROTAC: ubiquitination databases record sites on it.
Gene: Protein-coding gene on chromosome 9 (97,894,512 to 97,922,525, reverse strand). Ensembl gene ENSG00000136932.
Subcellular location (Human Protein Atlas): Nucleoplasm
Gene Ontology:
Molecular function: protein binding; tRNA (L-threonylcarbamoyladenosine(37)-C2) methyltransferase activity
Biological process: tRNA methylation
Genetic constraint (gnomAD): Loss-of-function variants: 20 observed, 30.39 expected, observed/expected ratio (o/e) 0.66, 90% interval 0.46 to 0.96. The upper end of that interval is the gene's LOEUF score, 0.96, which puts it in group 4 of 6, group 1 being the genes least tolerant of losing a copy. Missense variants: 528 observed, 542.92 expected, observed/expected ratio (o/e) 0.97, 90% interval 0.9 to 1.04. Synonymous variants: 227 observed, 198.78 expected, observed/expected ratio (o/e) 1.14, 90% interval 1.02 to 1.27.
Homologues: Orthologues: chimpanzee TRMO (98% identical), macaque TRMO (82% identical), dog TRMO (79% identical), guinea pig TRMO (72% identical), rabbit TRMO (70% identical), mouse Trmo (69% identical), rat Trmo (69% identical), tropical clawed frog trmo (47% identical), zebrafish trmo (37% identical), Drosophila melanogaster CG12822 (27% identical).
Diseases named in the same sentence as TRMO in open-access papers:
TRMO is named in the same sentence as 3 diseases in open-access papers, as found by Europe PMC text mining. Sharing a sentence is not in itself a finding about the gene and the disease. The quoted sentences say what the papers report.
thyroid cancer (3 papers, 2021 to 2025). "Although TRMO has previously been linked to thyroid cancer, its role in OSCC has yet to be elucidated." (PMID 40563552, 2025). "A mutation in TRMO has been associated with thyroid carcinoma." (PMID 40563552, 2025). "The altered expression of TRMO has been observed in patients with thyroid carcinoma, while altered TRNT1 expression was seen in colorectal cancer patients." (PMID 40563552, 2025).
TRMO also shares sentences with these, for which no sentence is quoted: colorectal cancer (1 paper); hypothyroidism (1).